RTN4 (reticulon 4)
Diseases named in the same sentence as RTN4 in open-access papers (continued):
Sharing a sentence is not in itself a finding about the gene and the disease.
heart failure (5 papers, 2013 to 2024). Inability of the heart to pump blood at an adequate rate to meet tissue metabolic requirements. "In diseases related to the heart, RTN4 has been shown to be involved in the regulation of coronary heart disease and is a key indicator of heart failure." (PMID 38994496, 2024). "These evidences suggest that myocardial ischemia may trigger Rtn4-mediated large scale programmed cell death of cardiomyocytes, which eventually leads to heart failure." (PMID 24564975, 2013).
diabetes (4 papers, 2018 to 2026). "In addition, we identify several proteins biomarkers to be associated with glycaemic deterioration in diabetes, including NogoR (RTN4), IL-18Ra, CRELD1, ENPP7 and FAS." (PMID 37137910, 2023). "To determine the effect of BMC grafts on the NMJs, we quantified transcript levels of Ras-related associated with diabetes (Rrad), cholinergic receptor, nicotinic, alpha 1 (Chrna1) and Reticulon-4 (NogoA), a well-known inhibitor of axonal regeneration and promoter of NMJ destruction." (PMID 29625589, 2018).
neuroblastoma (4 papers, 2013 to 2025). Neuroblastoma (NB) is the most common solid, extracranial childhood tumor. "Furthermore, RTN4 is intricately implicated in neuronal responses to hypoxia and oxidative stress, potentially contributing to neuroblastoma formation." (PMID 39969103, 2025).
non-small cell lung carcinoma (4 papers, 2021 to 2025). A group of at least three distinct histological types of lung cancer, including non-small cell squamous cell carcinoma, adenocarcinoma, and large cell carcinoma. "The CAA insertion/deletion polymorphism (rs34917480) of RTN4 may contribute to non-small cell lung cancer risk in Chinese population." (PMID 39972424, 2025). "The oncogenic roles of RTN4/Nogo have been investigated in various cancers, including oligodendroglioma; non-small-cell lung cancer; hepatocellular, cervical, colorectal, and nasopharyngeal carcinoma; as well as BC." (PMID 37511924, 2023). "Recent publications suggested that the RTN4 promoted angiogenesis in proliferative diabetic retinopathy via PI3K/Akt signal pathway and epithelial-mesenchymal transition in non-small cell lung cancer cells." (PMID 34194321, 2021). "In addition, RTN4 is necessary for the migration and contraction of airway smooth muscle cells in airway remodeling in chronic asthma, promoting angiogenesis in proliferative diabetic retinopathy via the PI3K/Akt signal pathway, and facilitating EMT in non-small cell lung cancer." (PMID 34194321, 2021).
osteosarcoma (4 papers, 2013 to 2025). A usually aggressive malignant bone-forming mesenchymal neoplasm, predominantly affecting adolescents and young adults. "The results revealed that high levels of RTN4 in osteosarcoma tissues as characterized by strong staining were positively associated with tumor metastasis and death of patients within 3 years via the manual scoring method." (PMID 39252612, 2025). "Given the functional significance of RTN4 in pyroptosis as well as osteosarcoma progression, the inhibition of RTN4 represents a potential strategy for tumor therapy." (PMID 39252612, 2025). "Meanwhile, high RTN4 expression has been confirmed in individuals with osteosarcoma as potential therapeutic target or biomarker." (PMID 39252612, 2025). "Next, we established an osteosarcoma xenograft mouse model using the K7M2 cells expressing RTN4 shRNA activated by dox." (PMID 39252612, 2025). "Among the top DEPs identifying fibroblastic groups from other pathological subtypes are POSTN, TPM4, RTN4, HNRNPK, and RACK1, which were directly associated with osteosarcoma progression and prognosis." (PMID 37681913, 2023). "To determine whether RTN4 plays a role in pyroptosis progression, we performed RTN4 silencing in osteosarcoma cell lines (U2OS, HOS, and 143B) and observed significant pyroptosis-associated “bubble” morphology by Annexin V-PI double staining." (PMID 39252612, 2025). "Furthermore, we detected RTN4 expression in paraffin-embedded specimens gathered from 101 patients with primary osteosarcoma by immunohistochemistry." (PMID 39252612, 2025). "In addition, we evaluated the immunohistochemical features of RTN4 in osteosarcoma tissues and normal bone tissues, which indicated a relatively high expression of RTN4 present in osteosarcoma tissues." (PMID 39252612, 2025). "Disrupting RTN4 (reticulon 4)-mediated ER remodeling may impair cancer pathogenicity in U2OS osteosarcoma cells by altering ER homeostasis and nuclear envelope assembly and disassembly during mitosis." (PMID 37681913, 2023).
spinal cord injury (4 papers, 2021 to 2026). Penetrating and non-penetrating injuries to the spinal cord resulting from traumatic external forces (e.g., WOUNDS, GUNSHOT; WHIPLASH INJURIES; etc.). "The myelin‐associated inhibitor Nogo‐A (Reticulon 4, RTN4) restricts axonal outgrowth, plasticity, and neural circuitry formation in experimental models of spinal cord injury (SCI) and is targeted in clinical interventions starting treatment within 4 weeks post‐SCI." (PMID 35698271, 2023).
breast tumor (3 papers, 2013 to 2023). "There is considerable evidence that links these nodes with breast tumor cell development and survival by exhibiting anti-apoptotic and/or modulatory signaling pathway activity, implying a significant connection of RTN4 PPIN with BC development." (PMID 37511924, 2023).
lung carcinoma (3 papers, 2012 to 2023). "YY1, RTN4, RICTOR, SFPQ, LARP6, and HELLS have been associated with cancers previously and, in this study, exhibited differential level changes between control, Idiopathic Pulmonary Fibrosis (IPF) and lung cancer cells." (PMID 37569873, 2023). "SFPQ, RTN4, HELLS, RICTOR, and LARP6 have high expression in lung cancer and other cancer cells and tissues." (PMID 37569873, 2023). "One important exception is SBTBN1 and RTN4 within cTOH3/aTOH1 (2p16.3–16.1), where over-expression occurs almost exclusively in controls relative to lung-cancer cases, irrespective of smoking status (OR = 0.000 and 0.08, p<0.0001)." (PMID 22384118, 2012).
osteoporosis (3 papers, 2020 to 2022). A condition of reduced bone mass, with decreased cortical thickness and a decrease in the number and size of the trabeculae of cancellous bone (but normal chemical composition), resulting in increased fracture incidence. "Circ-Rtn4 in the exosomes of bone marrow mesenchymal stem cells promotes osteogenesis and inhibits osteoporosis as a treatment for osteoporosis method." (PMID 35323799, 2022). "Further experiments showed that Rtn4-Exos attenuated TNF-α-induced cytotoxicity and apoptosis by sponging miR-146a, suggesting that Rtn4-Exos might serve as promising candidates for the treatment of TNF-α-induced osteoporosis." (PMID 32400849, 2020). "Hence, our findings suggested that Rtn4-Exos attenuated TNF-α-induced cytotoxicity and apoptosis in murine MC3T3-E1 cells by sponging miR-146a, suggesting that Rtn4-Exos may serve as novel candidates for treating osteoporosis." (PMID 32400849, 2020). "Our results showed that exosomes derived from circ-Rtn4-modified BMSCs (Rtn4-Exos) inhibited TNF-α-induced cytotoxicity and apoptosis in murine MC3T3-E1 cells via regulating miR-146a expression, thus indicating that Rtn4-Exos may serve as novel agents for the treatment of osteoporosis." (PMID 32400849, 2020).
astrocytoma (2 papers, 2018 to 2025). "Furthermore, in patients with WHO grade III astrocytoma, both the pathological type and high RTN4 expression were significantly associated with OS (p = 0.003, p = 0.001)." (PMID 39969103, 2025).
breast invasive ductal carcinoma (2 papers, 2013 to 2016). "In fact, previous study has shown that Reticulon-4 was overexpressed in human breast invasive ductal carcinoma and activated the epithelial-mesenchymal transition, indicating Reticulon-4 might be a metastasis-promoting molecule." (PMID 27811365, 2016).
cerebral infarction (2 papers, 2022 to 2025). An ischemic condition of the brain, producing a persistent focal neurological deficit in the area of distribution of the cerebral arteries. "Previously, we have demonstrated that inhibition of autophagic flux in blood vessels correlated with the degree of angiogenesis in the thalamus by RTN4 knockdown after cerebral infarction." (PMID 40735300, 2025).
dilated cardiomyopathy (2 papers, 2013 to 2016). Cardiomyopathy which is characterized by dilation and contractile dysfunction of the left and right ventricles. "RTN4, also called Nogo-A, is enriched in endoplasmic reticulum and known to be increased in genetic models of dilated cardiomyopathy and in end-stage heart failure in humans." (PMID 27378925, 2016). "It was also reported that Rtn4 expression was significantly increased in cardiac tissue from patients with dilated cardiomyopathy and from patients who have experienced an ischemic event (L6)." (PMID 24564975, 2013).
gastric cancer (2 papers, 2022 to 2025). A primary or metastatic malignant neoplasm involving the stomach. "Notably, RTN4 emerged as an independent prognostic indicator for gastric cancer." (PMID 39969103, 2025). "Moreover, differential expression of RTN4 is found in multiple cancers, which may function as a potential prognostic marker for gastric cancer." (PMID 34983537, 2022).
memory impairment (2 papers, 2023 to 2024). "Therefore, it can be inferred that EIF4EBP2 is related to the inferior temporal gyrus, which can cause memory impairment, and RTN4 is related to the middle temporal gyrus, which can cause alexia." (PMID 37238598, 2023).
prostate carcinoma (2 papers, 2023 to 2025). A carcinoma that arises from epithelial cells of the prostate gland. "In previous studies, the overexpression of RTN4 in prostate cancer cells was shown to block the cell cycle in the G2/M phase and to induce cell senescence and the expression of inflammatory cytokines, such as CHOP, IL-6, and tumor necrosis factor (TNF)-α, in a muscle cell line (C2C12)." (PMID 36768745, 2023).
Ureteral obstruction (2 papers, 2013 to 2025). Obstruction of the flow of urine through the ureter. "The RTN4 increased dramatically in unilateral ureteral obstruction and ischemia/reperfusion induced renal fibrosis." (PMID 39972424, 2025).
Werner syndrome (2 papers, 2023). "Moreover, ATP6V0D1 and RTN4 were highly expressed in cells of the patient with Werner syndrome (WF1 and WF2) compared with cells derived from healthy volunteers (NF) in WCL and were also highly detectable in sEVs from WF." (PMID 36768745, 2023). "Importantly, we identified ATP6V0D1 and RTN4 as novel markers that are frequently upregulated in sEVs from senescent and progeria cells derived from patients with Werner syndrome." (PMID 36768745, 2023). "Recently, novel senescent markers, ATP6V0D1 and RTN4, were shown to be increased in cells derived from patients with Werner syndrome, raising a possibility that they may serve as markers of disease progression." (PMID 37130431, 2023).
alcoholism (1 paper, 2020). "RTN4 has also been implicated in bipolar disorder, alcoholism, and pain, as well as is an increased in expression suicide blood biomarker in our studies." (PMID 30862937, 2020).
autism (1 paper, 2022). Persistent deficits in social interaction and communication and interaction as well as a markedly restricted repertoire of activity and interest as well as repetitive patterns of behavior. "In NPCs, we continued to see evidence for disruption in NOGO signaling through increased expression of both NOGO (RTN4) and the TRKA receptor (NTRK1), which is associated with autism through rare protein-coding variation, is a known interactor with P75 and is modulated by NOGO signaling." (PMID 35760976, 2022).
bladder cancer (1 paper, 2021). "On the other hand, increasing the expression of SMARCAD1 and RTN4 decreases the incidence of death from bladder cancer." (PMID 34589136, 2021).
cholesteatoma (1 paper, 2022). A pathologic process characterized by the proliferation of keratinizing squamous epithelium resulting in the accumulation of keratin and cells in the middle ear and/or mastoid. "However, in our own middle ear expression dataset from the same patients, all 12 genes were DEGs for cholesteatoma: RTN4, RAB5A, CRYBG1, RGS22, HEPHL1, and SPTLC3 were upregulated, while APBB1IP, BHLHE41, ARID3A, C5AR1, CPT1B, and FAM227A were downregulated." (PMID 36699445, 2022).
COVID-19 (1 paper, 2023). A disease caused by infection with severe acute respiratory syndrome coronavirus 2. "SARS-CoV-2, an etiological agent of COVID-19, is found to occupy the RTN4 gene, thereby enhancing the development of virally induced double-membrane vesicles, which is crucial for the replication of the viral genome." (PMID 37834358, 2023). "Results from the DPI analysis showed that the genes GFAP and RTN4 were found to be involved in COVID-19 with a score of 0.885 and 0.692." (PMID 37834358, 2023).
dementia (1 paper, 2023). Loss of intellectual abilities interfering with an individual's social and occupational functions. "Importantly, five of these pre-mRNAs (DOCK1, HOMER1, MAN2A1, RTN4, and ST18) were also found to correlate with dementia severity in the parietal cortex, suggesting that these circRNAs in general correlate with AD progression." (PMID 37266374, 2023).
endometrial cancer (1 paper, 2023). Primary or metastatic malignant neoplasm involving the endometrium (mucous membrane that lines the endometrial cavity). "The incorporation of RTN4, LAMP2, WDR1, KRT13, ALDH2 and ILF3 gave rise to a ten-marker biomarker panel, which predicted endometrial cancer with an AUC of 0.91 (0.86–0.96), and was the best performing diagnostic model." (PMID 36807337, 2023).
endometriosis (1 paper, 2018). The growth of functional endometrial tissue in anatomic sites outside the uterine body. "They identified CLIC4, RTN4, and VCL as the target genes, and proposed that upregulation of miR-199a in endometriosis regulates adhesion and infiltration of endometrial cells by targeting these genes." (PMID 29463003, 2018).
ischemic cardiomyopathy (1 paper, 2021). Ischemic cardiomyopathy is a cardiomyopathy in which a weakness in the muscle of the heart due to inadequate oxygen delivery to the myocardium with coronary artery disease being the most common cause. "Rtn4 was previously only shown to be dysregulated in ischemic cardiomyopathy on whole tissue level but, to the best of our knowledge, was never shown to be specifically upregulated in a subset of cardiomyocytes with a hypertrophy-associated transcriptome." (PMID 33514846, 2021).
keloid (1 paper, 2016). An irregularly shaped, elevated mark on the skin caused by deposits of excessive amounts of collagen during wound healing. "Our data have demonstrated that inhibited proliferation of keloid fibroblasts due to the suppression of PTB is accompanied with the alternate splicing of USP5 and RTN4, which may be correlated to over proliferation of fibroblasts in keloid." (PMID 27897224, 2016). "PTB knockdown significantly slowed the proliferation of keloid fibroblasts and accelerated the regression of transplanted keloid tissues, which was accompanied by a shift in the alternative splicing of USP5 and RTN4." (PMID 27897224, 2016).
Listeria infection (1 paper, 2015). "Here again we could validate the endogenous modification of RTN4 by ISG15 following Listeria infection by detecting multiple distinct slower migrating bands of RTN4 and ISG15." (PMID 26259872, 2015).
migraine (1 paper, 2019). "Here we investigated a potential link between migraine and five key Nogo-type signaling genes: RTN4, OMGP, MAG, RTN4R and LINGO1, by screening 15 single nucleotide polymorphisms (SNPs) within these genes." (PMID 31861860, 2019).
primary progressive MS (1 paper, 2022). "Evidence supporting the application of this protein as a biomarker in MS was also provided by studies reporting the presence of RTN4 in CSF of patients regardless of stage and type of disease (remitting–relapsing and primary progressive MS)." (PMID 35887886, 2022).
prostate tumor (1 paper, 2024). "This suggested that RTN4 might somehow be involved in prostate tumor progression which opens up the potential for the creation or identification of selective agents targeting RTN4 for PCa therapy." (PMID 38790213, 2024).
psychosis (1 paper, 2024). "Association analyses of age-at-onset, number of mood episodes, and presence of psychosis, substance abuse and/or suicidal ideation suggested modest contributions of genes such as RTN4, XKR4, NRXN1, NRG1/3 and GRK5 to disease characteristics." (PMID 38570518, 2024).
sarcoma (1 paper, 2025). A usually aggressive malignant neoplasm of the soft tissue or bone. "Here, we found that RTN4B is the predominant isoform of RTN4 expressed in various tumors, especially in sarcoma by the cancer genome atlas (TCGA) database analysis." (PMID 39252612, 2025).
α-synucleinopathy (1 paper, 2021). "The results of our study confirm the association of RTN4 with crucial for some neurodegenerative disease processes, including amyliodopathy, neurodegeneration, and α-synucleinopathy." (PMID 34830564, 2021).